IL22 (interleukin 22)
Diseases named in the same sentence as IL22 in open-access papers (continued):
Sharing a sentence is not in itself a finding about the gene and the disease.
cancer (continued). "In addition, N8-acetylspermidine, TMA, and choline induced the expression of the inflammatory cytokines IL-8 and IL-22, which are also known to induce cancer cell growth and survival." (PMID 33430687, 2021). "IL-22 is often described as a cytokine with different roles in some cancer entities." (PMID 33851257, 2021). "Innate lymphoid cells 3 could be responsible for the occurrence of HPD because these cells can promote cancer development by secreting the cytokines IL-17, IL-22, and GM-CSF in an antigen-independent manner." (PMID 34135884, 2021). "Thus, an investigation focusing on understanding the IL-22/IL-22BP axis in this area of cancer research is highly warranted." (PMID 33851257, 2021). "In different circumstances IL-22 may contribute to pathological conditions or act as a cancer promoting cytokine secreted by infiltrating immune cells." (PMID 35295139, 2021). "The current knowledge of IL‐22 function is based on advanced‐stage cancer cell line models where it has been shown that IL‐22 stimulates cell proliferation, transformation, and migration in human/mouse cancer cell lines." (PMID 31725949, 2020). "Next, we investigated if this correlation of IL‐22 with malignancy occurs in human cancer." (PMID 31725949, 2020). "Next, we investigated whether IL‐22 can enhance migration and invasive behavior of cancer cells in vitro." (PMID 31725949, 2020). "These characters render a cancer-promoting function of IL-22 in epithelial cancers." (PMID 32649314, 2020). "Similarly, the downregulation of IL‐22BP and upregulation of IL‐22 levels during the invasion stage explain the responsiveness of cancer cells to IL‐22." (PMID 31725949, 2020). "In cancer, the role of IL‐22/IL‐22RA1 axis is complex and context‐dependent." (PMID 31725949, 2020). "The discrepancy of cancer cells in response to IL‐22 stimulation in in vivo and in vitro systems could be due to the presence of IL‐22BP in the TME during these stages." (PMID 31725949, 2020). "In general, IL-22 is considered to have protective effects at barrier sites exposed to external stimuli in an acute setting, however, chronic inflammation can result in dysregulation of IL-22 signaling, promoting overt tissue damage and cancer." (PMID 33003458, 2020). "However, accumulating evidence suggests pivotal role of IL-22 in instigation of various cancers due to its pro-inflammatory and tissue repairing activity." (PMID 33042126, 2020). "Furthermore, the levels of IL-22/IL-22R1 axis also differ in early and late cancers which shows its potential to be used as a staging marker in the future." (PMID 33042126, 2020). "We know that IL-22 is a protective factor for the liver, by promoting the regeneration of tissue, increasing the function of the barrier, reducing the chronic inflammation and preventing the occurrence of cancer." (PMID 32760208, 2020). "This upregulation of IL‐22BP expression during cell proliferation stages may have a neutralizing effect on IL‐22 and prevented its proliferative action on cancer cells." (PMID 31725949, 2020). "Importantly, many studies found that IL-22 was closed related to progression and metastasis of many cancer, including breast, lung, and gastric cancer." (PMID 31823782, 2019). "Therefore, a similar function resulting in maintaining the cancer stem cell niche is likely to be one of the main contributions of IL-22 to colorectal carcinogenesis." (PMID 28492497, 2017). "The elevated IL-22 levels found in patients with pulmonary manifestations of extrathoracic tumours support the hypothesis that IL-22 may be a mediator in cancer development and progression." (PMID 27388918, 2016). "The membranous and cytoplasmic expression of IL-22R1 and IL-10R2 were detected by immunofluorescence in the two GBM cell lines, in agreement with the transcriptional and western blot studies, suggesting that GBM cancer cell lines have the ability to respond to IL-22 stimulation." (PMID 25793261, 2015).
cancer (continued). "The TTP-dependent regulatory pathway described herein likely contributes to the role of IL-22 in inflammation and cancer and may evolve as novel target for pharmacological IL-22 modulation." (PMID 26486958, 2015). "Besides, the cytokine member IL-22, which is mainly secreted by the T cells subsets, Th17 and Th22 subsets and innate lymphoid cells (ILCs), has also been used in cancer immunotherapy." (PMID 25590298, 2015). "In human liver cancer cells, IL-22-induced STAT3 activation promoted at least three hallmarks of cancer (proliferation, survival and angiogenesis) via the upregulation of a variety of mitogenic (cyclin D1, c-myc, and Rb2), anti-apoptotic (Bcl-2 and Bcl-xL), and angiogenic (VEGF) genes." (PMID 23316374, 2012). "Several studies focusing on the effects of IL-22 on cancer cells have shown similar results." (PMID 21625390, 2011). "Thus, a delicate balance between IL-22 and IL-22BP is generally needed physiologically, since both the lack of IL-22 as well as its uncontrolled expression can lead to pathogenesis such as infections or cancer development, respectively." (PMID 36551508, 2022). "Interestingly, cancer cells release IL-1, which stimulates IL-22 production by memory T cells." (PMID 34300224, 2021). "However, the number of IL‐22‐positive cells significantly increased in invasive DC and/or metastatic‐to‐lymph node (LN) DC validating the link between IL‐22 expression and invasiveness of cancer cells." (PMID 31725949, 2020). "Interestingly, an inhibition in early carcinoma or malignant transition stage (10 weeks) was observed in IL‐22−/−/PyMT tumors as epithelial cells were still confined by basement membrane, which is depicted by positive staining of basement membrane marker laminin‐α1." (PMID 31725949, 2020). "Thus, IL-22 may play a role in the attenuation of drug-induced apoptosis by the increasing the expression of SERPINB3/B4 in cancer cells." (PMID 22922995, 2012). "We also found that IL-22 induces G2/M cell cycle arrest without causing cancer cell apoptosis." (PMID 21625390, 2011). "Cytokines such as IL-1, IL-6, TNF, and others (TGF-β, IL-22, IL-11) interact with cancer cells, promoting signaling pathways (e.g., IKK-NF-κB, JAK-STAT3, MAPK-AP1) that support cancer progression." (PMID 39996799, 2025). "Many well-known proteins that play crucial roles in cancer like IL10, USP18, and IL22 were included in this network." (PMID 37697300, 2023). "The JAK/STAT3 pathway is the main signal transduction pathway of IL-22, and the activation of STAT3 promotes the invasion ability of malignant tumors." (PMID 35669104, 2022). "By using the AOM-DSS cancer model, it has been determined that IL-17D binds to the CD93 receptor, regulating IL-22 secretion in ILC3s." (PMID 36341381, 2022). "IL-22 production has also been shown to promote CRC development, possibly by direct effects on stem cells or by enhancing cancer cell proliferation." (PMID 34296212, 2021). "Upon induction of intestinal inflammation by Helicobacter hepaticus and of cancer formation with the carcinogen azoxymethane (AOM), ILC‐derived IL‐22 acts on epithelial cells and induces cancer formation." (PMID 31777064, 2020). "Importantly, IL-22 was found to enhance PC stemness through IL-22RA1/STAT3 signaling, elucidating the role of microenvironmental factors in regulating cancer stemness." (PMID 40806452, 2025). "Daily consumption of dark tea can achieve cancer prevention by inhibiting pro-inflammatory cytokines TNF-α, IL-1β, and IL-6 and increasing anti-inflammatory cytokines IL-10 and IL-22, which is mainly attributed to the down-regulation of the NF-κB signaling pathway." (PMID 37764687, 2023). "The Candida albicans (C. albicans)-driven release of IL-7 from macrophages promotes aryl hydrocarbon receptor (AhR) and phospho-STAT3 (p-STAT3) binding at the IL-22 gene in ILC3s, which subsequently triggers the transcription of this cytokine for CAC formation in C. albicans AOM-DSS cancer model." (PMID 36341381, 2022).
cancer (continued). "In conclusion, IL-22 derived from TH17 cells, TH22 cells, and potentially other sources can promote HCC progression through different mechanisms, mainly acting through the cancer cells." (PMID 33851257, 2021). "In all cancer tissues, regardless of degree of differentiation, the value of Il-21/IL-22 mRNA ratio was higher comparing to a control group (respectively: G1 vs. C p = 0.003405; G2 vs. C p = 0.008114; G1 vs. C p = 0.007473)." (PMID 34300224, 2021). "Higher expression of OLFM4, a cancer stemness gene induced by IL-22, is present in PSC-UC, suggesting that IL-22 responses may result in alterations of the intestinal stem-cell niche in these patients." (PMID 33570127, 2021). "In the case of IL22, we did not observe any differences in the number of mRNA copies between the cancer specimens and the control group, as well as between the G1, G2, and G3 histologically differentiated groups." (PMID 34300224, 2021). "IL-22 was also shown to have immunosuppressive functions in other cancer, though it was not well studied in HCC so far." (PMID 23316374, 2012). "However, we have not gone into detail about the major impact microbiota and IL-22 have on cancer development." (PMID 33003458, 2020). "The diverse roles of IL-22 in cancer immunity are still not clear." (PMID 32670290, 2020). "However, the effect of IL-22 on aerobic glycolysis in cancer cells has not been investigated until date." (PMID 28445985, 2017). "Whether IL-22 and IL-22Rα are involved in the development of skin diseases, including inflammation and cancer, has not yet been reported." (PMID 28558005, 2017). "Our present study shows that IL-22 affects several important functions of OSCC cells via the STAT3-dependent and/or -independent pathways, suggesting that IL-22 may play a role in carcinoma cell differentiation and the upregulation of SERPINB3/B4, well-known biomarkers for SCC." (PMID 22922995, 2012). "Additionally, IL-22 upregulates expression of Erk1/2-independent genes such as Discoidin domain receptor tyrosine kinase 2 (DDR2), Lipocalin 2 (LCN2), and Leucine-rich alpha-2-glycoprotein 1 (LRG1), known for their involvement in the modulation of specific cancer hallmarks." (PMID 40806452, 2025). "Indeed, seletalisib totally inhibited IL-22-induced STAT3 phosphorylation in Tyr705 at 30 min and 1 h of stimulation, thus suggesting a possible molecular link between PI3Kδ and STAT3 in human keratinocytes, as previously demonstrated in PI3K-transformed cancer cells." (PMID 34685616, 2021).
bacterial infection (96 papers, 2009 to 2025). "IL-22, a cytokine integral to the innate immune response and produced by macrophages, has been associated with both fetal injury and protection from bacterial infection." (PMID 40563964, 2025). "In a mouse model of ACLF, treatment with IL‐22 therapy, provided in the form of IL‐22Fc (two IL‐22 molecules linked to an immunoglobulin constant region), promoted liver repair and reduced bacterial infection." (PMID 36800487, 2025). "For example, AHR agonists in the gastrointestinal tract appear to enhance barrier function in part through enhanced IL22 expression, which in turn helps protect the gut from pathogenic bacterial infection and genotoxic stress." (PMID 40077746, 2025). "A deficiency in AHR leads to fewer RORγt+ ILC with diminished IL-22 production, thus inhibiting protection against intestinal bacterial infections." (PMID 39309440, 2024). "Our results confirmed that the expression of antimicrobial peptides (AMPs) and IL-22 was restrained and the susceptibility to bacterial infection was increased in VD-deficient zebrafish." (PMID 36879441, 2023). "The well-documented effect of IL-22 in maintaining microbial homeostasis is mainly achieved by preventing and defending against pathogenic bacterial infections." (PMID 35432360, 2022). "IL-36R signaling promotes IL-23/IL-22/antimicrobial peptide and IL-6/IL-22/antimicrobial peptide-mediated inhibition of intestinal pathogenic bacterial infection by integrating innate and adaptive immune responses." (PMID 35216425, 2022). "During intestinal pathogenic bacterial infection, innate immune cells in mice are activated and produce IL-23 and IL-22 to promote antimicrobial peptide production and bacterial clearance." (PMID 35216425, 2022). "On the other hand, IL-22, a cytokine secreted by innate lymphoid cells upon infection with pathogenic bacteria enhances defense against bacterial infection by producing mucus and antimicrobial proteins in intestinal epithelial cells." (PMID 35463998, 2022). "Given the similarity between COVID-19 and the Flu for the risk of the exacerbation of secondary bacterial infection, a beneficial effect of IL-22 in limiting disease severity has also recently been proposed for SARS-CoV-2 infection." (PMID 34209845, 2021). "IL-22 plays crucial role in protecting the skin, gastrointestinal and respiratory tract from both pathogenic and commensal bacterial infections." (PMID 33042126, 2020). "Mice deficient in IL-22 or ILC3s are more susceptible to many different bacterial infections, especially mucosal-associated pathogens." (PMID 29059238, 2017). "IL-22-deficient mice displayed exaggerated intestinal inflammation and impairment of the epithelial barrier and rapidly succumbed to bacterial infection." (PMID 28794449, 2017). "Although the IL-17 cytokine family is associated with cells of the adaptive arm of the immune system, in bacterial infections such as those caused by P. aeruginosa, innate immune cells are the first responders in secretion of IL-17, IL-21, IL-22, and IL-23." (PMID 28680858, 2017). "Il17 and Il22 were also increased in the bladders of Rag2−/− mice that are deficient in γδ T cells and Th17 cells, suggesting that ILC3s can act as a source of these cytokines during bacterial infection in the bladder." (PMID 35845169, 2022). "Furthermore, relative deficiency of IL-22 is seen in Acne Inversa patients which occurs due to chronic inflammation caused by persistence cutaneous bacterial infection." (PMID 33042126, 2020). "To study the impact of bacterial infection on host immunological responses, we monitored mRNA levels of genes encoding inflammation markers TNFα, IL-1β, IL-22 and IL-10, including pro- and anti-inflammatory cytokines, in axenic and infected zebrafish larvae at 1, 2 and 3 dpi." (PMID 22911651, 2012).
bacterial infection (continued). "Alternatively, immune status (that is, IL-22 deficiency) has been linked to the abundance of Lactobacillus, potentially suggesting that these seasonal changes might be in part driven by the host response to bacterial infection." (PMID 26023870, 2015). "We used qRT-PCR to quantify the expression of inflammatory genes commonly elevated in bacterial infections including the chemokine Cxcl1, cytokines (Il22, Il17a, and Il6), and the bactericidal antimicrobial peptide Reg3g." (PMID 41502946, 2025). "Although IL-17 and TH17 cells can cause inflammation and damage the intestinal mucosa, IL-17 and IL-22 also play a protective role in limiting intestinal fungal and bacterial infections." (PMID 40746559, 2025). "As a consequence, GPR183 and 7α,25-OHC promotes ILC3-mediated protective immunity against bacterial infection by increasing the number of IL-22-producing ILC3s in the intestine." (PMID 41467015, 2025). "Overall, this study not only provides new insights for understanding the immune function of IL-22 in fish, but also provides potential molecular targets for the development of new therapeutics and molecular breeding strategies against bacterial diseases." (PMID 39211040, 2024). "It is noteworthy that, under conditions of bacterial infection, the antioxidant capacity of IL-22 is believed to play a vital role in maintaining the homeostasis of the internal environment in mammals." (PMID 39211040, 2024). "These bacteria affect the development and maturation of Th17 cells, which control mucosal fungus and bacterial infections by producing IL-22, IL-21, IL-17F, and IL-17A cytokines." (PMID 38254678, 2024). "In the case of this study, managing ROS within TH17 cells in the gut was shown to be essential to sustain the production of IL22 cytokine to maintain gut homeostasis in response to bacterial infection." (PMID 39544255, 2024). "RA was administered after bacterial infection; thereafter, γδ T-cells were induced to produce IL-22 by specific and direct binding to the IL-22 promoter, thus regulating the transcription of IL-22 mRNA." (PMID 38254678, 2024). "Limiting bacterial infection by reducing IL-22 production through induction of ILC3 death appears to be a potential host defense mechanism against S. typhimurium infection." (PMID 37122757, 2023). "We next analyzed levels of the IL-10 family cytokine IL-22, which has been demonstrated to be crucially involved in protecting the intestinal epithelium from bacterial infections and which can be promoted upon the induction of type 1 immune responses." (PMID 36810248, 2023). "RegIII proteins belong to the group of antimicrobial lectins that are needed for protection against bacterial infections and their expression is triggered by IL-22." (PMID 36430676, 2022). "For instance, proper wound healing and defense against bacterial infections are controlled by AhR-dependent IL-22 secretion from innate and adaptive cells." (PMID 36601108, 2022). "Tryptophan metabolites produced by intestinal microflora during induction of colitis by bacterial infection in mice are known to play a protective role in the pathogenesis of the disease through AhR activation, which enhances IL-22 secretion." (PMID 35463998, 2022). "Injection of IL-1α, TNFα, OSM, IL-22 and IL-17 together in the wound edges induced delayed wound healing similar to that induced by the bacterial infection." (PMID 36275755, 2022). "Expression of IL-22 and IL-17 during viral lung infections also promotes prevention of secondary bacterial infections." (PMID 33968082, 2021). "IL-22 has been identified in several teleost species and is also induced in response to bacterial infections." (PMID 34759916, 2021). "IL-22 also induces certain AMPs, such as β-defensin and hepcidin, in response to bacterial infection." (PMID 34759916, 2021).